NSUN6 (NOP2/Sun RNA methyltransferase 6)
Description:
S-adenosyl-L-methionine-dependent methyltransferase that specifically methylates the C5 position of cytosine 72 in tRNA(Thr)(TGT) and tRNA(Cys)(GCA). In vitro also methylates tRNA(Thr)(AGT). Methylation requires, in the acceptor stem region, the presence of the 3'-CCA terminus, the target site C72, the discriminator base U73, and the second and third base pairs (2:71 and 3:70) in the tRNA substrates.
Synonyms: NOPD1; FLJ23743; 4933414E04Rik; ARL5B-AS1; MRT82
Tractability: Small molecule: a structure with a bound ligand is known. PROTAC: ubiquitination databases record sites on it; its protein half-life has been measured.
Target class: Enzyme; Transferase
Gene: Protein-coding gene on chromosome 10 (18,545,561 to 18,659,285, reverse strand). Ensembl gene ENSG00000241058.
Subcellular location: Cytoplasm
Subcellular location (Human Protein Atlas): Golgi apparatus
Pathways (Reactome):
Metabolism of RNA: tRNA modification in the nucleus and cytosol
Gene Ontology:
Molecular function: tRNA (cytidine-5-)-methyltransferase activity; tRNA binding; rRNA (cytosine-C5-)-methyltransferase activity; methyltransferase activity; RNA binding; RNA methyltransferase activity; S-adenosylmethionine-dependent methyltransferase activity
Biological process: tRNA C5-cytosine methylation; tRNA methylation; tRNA modification; rRNA base methylation
Cellular component: cytoplasm; cytosol
Genetic constraint (gnomAD): Loss-of-function variants: 16 observed, 15.66 expected, observed/expected ratio (o/e) 1.02, 90% interval 0.69 to 1.55. The upper end of that interval is the gene's LOEUF score, 1.55, which puts it in group 6 of 6, group 1 being the genes least tolerant of losing a copy. Missense variants: 232 observed, 186.82 expected, observed/expected ratio (o/e) 1.24, 90% interval 1.12 to 1.38. Synonymous variants: 73 observed, 71.81 expected, observed/expected ratio (o/e) 1.02, 90% interval 0.84 to 1.24.
Homologues: Orthologues: macaque NSUN6 (98% identical), chimpanzee NSUN6 (95% identical), dog NSUN6 (88% identical), rabbit NSUN6 (88% identical), pig NSUN6 (86% identical), mouse Nsun6 (81% identical), rat Nsun6 (80% identical), tropical clawed frog nsun6 (68% identical), zebrafish nsun6 (57% identical), Drosophila melanogaster CG11109 (39% identical). Paralogues in human: NOP2 (25% identical), NSUN5 (18% identical).
Diseases named in the same sentence as NSUN6 in open-access papers:
NSUN6 is named in the same sentence as 41 diseases in open-access papers, as found by Europe PMC text mining. Sharing a sentence is not in itself a finding about the gene and the disease. The quoted sentences say what the papers report.
pancreatic cancer (17 papers, 2021 to 2025). "Moreover, NSUN6 is associated with prognosis of various cancers, including pancreatic cancer and hepatocellular carcinoma." (PMID 35309925, 2022). "Overexpression of NSUN6 in pancreatic cancer cells inhibits cell proliferation, and low NSUN6 expression is associated with poor patient survival, indicating its potential as an independent prognostic factor for predicting recurrence and survival in pancreatic cancer." (PMID 40370440, 2025). "In vitro (a pancreatic cancer cell line) and in vivo (xenograft mouse model) studies have demonstrated that NSUN6 inhibited cell proliferation through the cell cycle." (PMID 41462962, 2025). "NSUN6 expression was downregulated in pancreatic cancer tissue samples, where NSUN6 expression correlated with clinical pathological parameters, including T staging and the Ki-67+ cell ratio." (PMID 41462962, 2025). "The m5C methyltransferase, NSUN6 was indicated to suppress pancreatic cancer development by controlling cell proliferation." (PMID 40351534, 2025). "Significantly reduced expression of NSUN6 was observed in pancreatic cancer tissues compared to normal controls." (PMID 40351534, 2025). "In contrast to normal pancreatic tissues, the protein level of NSUN6 is reduced in pancreatic cancer tissues." (PMID 40370440, 2025). "Regression analysis indicates that ALYREF and NSUN6 function as independent prognostic biomarkers for predicting pancreatic cancer outcomes." (PMID 40114967, 2025). "Abnormal expression of NSUN6 is an important factor involved in the regulation of pancreatic cancer cell proliferation." (PMID 38468490, 2024). "The role of NSUN6 in regulating cell proliferation and pancreatic cancer tumor growth was recently confirmed, and NSUN6 performs well in evaluating tumor recurrence and survival among pancreatic cancer patients." (PMID 35281843, 2022). "Conversely, NSUN6 confers cellular fitness advantages and functions as a tumor suppressor in pancreatic cancer." (PMID 34394351, 2021). "Additionally, ALYREF has been shown to promote tumor growth and increase Ki-67 expression in tumor tissues, while NSUN6 inhibits pancreatic cancer cell proliferation and in vivo tumor growth." (PMID 40114967, 2025). "NSUN6 regulated cell proliferation and was shown to be down-regulated in pancreatic cancer." (PMID 39340806, 2024). "This suggested that NSUN6 may influence pancreatic cancer proliferation by regulating CDK10 expression involved in mitotic spindle assembly and mitotic nuclear division." (PMID 38476632, 2024). "Indeed, processes associated with cell proliferation, such as the cell cycle and G2/M checkpoint, were also found to be enriched in the group of pancreatic cancer patients with lower expression of NSUN6." (PMID 38476632, 2024). "Low expression of NSUN6, an m5C methyltransferase, was found in pancreatic cancer patients, and may contribute to pancreatic cancer cell proliferation through regulation of CDK10." (PMID 35350378, 2022). "Contrary to findings in other cancers where m5C methyltransferases are often overexpressed, the reduced expression of NSUN6 in pancreatic cancer suggests it may act as a protective factor, though the role of NSUN6 in mediating RNA m5C modifications warrants further investigation." (PMID 40370440, 2025). "Conversely, NSUN6 and DNMT3A have exhibited inhibitory impacts on pancreatic cancer, effectively curbing the proliferation of malignant cells." (PMID 40008496, 2025). "Studies have revealed abnormal expression patterns of m5C methyltransferases, including NSUN2 and NSUN6, as well as m5C-binding proteins like YBX1 and ALYREF, in cancers such as esophageal, gastric, hepatocellular, colorectal, and pancreatic cancers." (PMID 40114967, 2025).
pancreatic cancer (continued). "The role of NSUN6 in cancer development remains unclear, but studies have shown that NSUN6 acts as a protective factor against triple-negative breast cancer (TNBC), pancreatic cancer, testis cancer, thyroid cancer and ovary cancer but is a risk factor for CRC." (PMID 37325635, 2023). "In addition, NSUN6, NSUN7, and DNMT3B exhibited downregulated trends in pancreatic cancer." (PMID 35864471, 2022).
breast carcinoma (10 papers, 2021 to 2025). "We performed GSEA to identify the abnormally activated signaling pathways of NSUN2 and NSUN6 that cause their differential expression in breast cancer." (PMID 33928086, 2021). "For instance, NSUN5 and NSUN6 were reported to be associated with metastasis in skin cancer and breast cancer." (PMID 34512153, 2021). "However, NSUN6 expression was associated with a poor prognosis in breast cancer, and with a more favorable prognosis in colorectal cancer." (PMID 36060802, 2022). "For example, in breast cancer, NSUN6 expression is elevated in bone metastases, and NSUN6-mediated m5C on specific transcripts is associated with activation of YAP signaling, promoting osteotropic metastasis." (PMID 41301491, 2025). "NSUN6 regulates the mammalian sterile 20-like kinase 1 (MST1) target gene of Yes-associated protein 1 (YAP1), leading to osteoclast differentiation and breast cancer bone metastasis." (PMID 40370440, 2025). "NSUN6 has also been shown to inactivate macrophage stimulating 1 (MST1) and activate yes-associated protein (YAP) target genes in breast cancer through m5C modification, thereby triggering osteoclast differentiation and bone metastasis." (PMID 35562754, 2022). "This further confirms that NSUN2 and NSUN6 are related to the tumorigenesis of breast cancer, consistent with the findings of previous studies." (PMID 33928086, 2021). "Meanwhile, NSUN6 showed medium expression in normal breast glands and high expression in breast cancer tissues." (PMID 33928086, 2021). "The analysis of the cBioPortal database in this study showed that NSUN2 and NSUN6 have a high frequency of gene alterations in breast cancer patients." (PMID 33928086, 2021). "Given that NDRG1 significantly promotes tumor progression and brain metastasis in aggressive breast cancer, NSUN6 may potentially co-drive breast cancer radioresistance via NDRG1 regulation." (PMID 40823093, 2025). "The pathological functions of NSUN6 have been reported in the context of human cancer: the overexpression of NSUN6 repressed the proliferation of liver cancer cells, and the knockdown of NSUN6 repressed the migration of breast cancer cells." (PMID 35743028, 2022). "In addition, analysis using the HPA database showed that NSUN2 and NSUN6 were also abnormally expressed at the protein level in breast cancer tissues." (PMID 33928086, 2021). "In breast cancer cells, NSUN6 can form a complex with the proteins LLGL2 and lncRNA Maya, which inactivates the kinase Hippo/MST1 through methylation of Hippo/MST1, resulting in promotion of tumor metastasis." (PMID 34630524, 2021). "Moreover, we unexpectedly found that NSUN6 is closely related to the stage of breast cancer." (PMID 33928086, 2021). "NSUN2 and NSUN6 influence tumorigenesis and the tumor immune microenvironment (TIM) in breast cancer." (PMID 40370440, 2025). "NSUN2 and NSUN6 affect tumorigenicity and the tumor immune microenvironment (TIM) of breast cancer." (PMID 35562754, 2022). "To determine the mechanism by which NSUN2 and NSUN6 affected the prognosis of TNBC patients, we used the UALCAN online database to analyze 1,097 primary breast cancer samples and 114 normal breast samples in TCGA according to molecular subtypes and histological classification." (PMID 33928086, 2021).
glioma (7 papers, 2020 to 2025). A benign or malignant brain and spinal cord tumor that arises from glial cells (astrocytes, oligodendrocytes, ependymal cells). "We obtained six genes associated with prognosis (P < 0.01), among which NOP2, NSUN2, NSUN4, NSUN5, and NSUN7 acted as risk factors (HR > 1), and NSUN6 played a protective role (HR < 1) in gliomas." (PMID 32974125, 2020). "The loss of NSUN6 conferred resistance to susceptible glioma cell lines." (PMID 41462962, 2025). "Subsequent phenotypic assays, including CCK‐8 viability tests, colony formation assays and scratch wound healing assays, consistently demonstrated that NSUN6 overexpression significantly inhibited glioma cell proliferation and migration." (PMID 40561176, 2025). "Data from the Human Protein Atlas (HPA) further confirmed that NSUN6 expression is elevated in glioma tissues compared to normal brain." (PMID 40561176, 2025). "NSUN6 was identified as a key protective gene whose overexpression inhibited glioma cell proliferation and migration in vitro." (PMID 40561176, 2025). "Future studies involving transcriptomic profiling, m5C mapping and pathway perturbation are needed to uncover the specific biological targets and regulatory networks through which NSUN6 mediates its tumor‐suppressive effects in glioma." (PMID 40561176, 2025). "To verify the role of NSUN6 expression in glioma cells, we constructed an NSUN6 overexpression plasmid and conducted experiments on the LN229 and U251 glioma cell lines." (PMID 40561176, 2025). "To experimentally validate its function, we overexpressed NSUN6 in two glioma cell lines (LN229 and U251) using plasmid transfection." (PMID 40561176, 2025). "Applying univariant and multivariant CoxPH analysis, we proved that ALYREF, DNMT3B, NSUN4 and NSUN6 were independent prognostic factors for glioma." (PMID 37934565, 2023). "The results showed that NSUN4, NSUN7, DNMT1, DNMT3B, DNMT3A, NOP2 and NSUN5 were negatively correlated with the overall survival of low‐grade glioma, while NSUN6 was positively correlated with the overall survival." (PMID 33400376, 2021). "NSUN6 affects both large and small RNA to control glioma response to therapy." (PMID 41462962, 2025). "Among these genes, NSUN6 emerged as a key protective factor, supported by single‐cell transcriptomics, protein expression data from the Human Protein Atlas and functional assays in glioma cell lines." (PMID 40561176, 2025). "Additionally, a chi‐square test of the HPA data revealed significant differences in NSUN6 expression between glioma and normal tissues." (PMID 40561176, 2025). "In gliomas, emerging evidence supports a protective role for NSUN6." (PMID 40561176, 2025). "According to a recent study on gliomas, five genes related to m5C methyltransferase were identified to construct a risk signature (5MM) and were used to predict glioma prognosis, including NOP2, NSUN4, NSUN5, NSUN6 and NSUN7." (PMID 36637205, 2023). "NSUN6 is a key protective gene whose overexpression inhibits the proliferation and migration of LN229 and U251 glioma cell lines in vitro." (PMID 41462962, 2025). "Through survival analysis, this study constructed a low‐grade glioma prognostic model with 4 genes (NSUN4, NSUN7, DNMT1 and NSUN6) and drew a nomogram accordingly." (PMID 33400376, 2021). "All five RNA:m5C methyltransferase genes, NOP2, NSUN4, NSUN5, NSUN6, and NSUN7, were differentially expressed between normal brain tissues, low grade and high grade glioma tissues." (PMID 32974125, 2020). "Second, we have only preliminarily validated the effects of key genes – particularly NSUN6 – on glioma cells in vitro, without fully elucidating their downstream molecular mechanisms." (PMID 40561176, 2025).
glioblastoma (6 papers, 2020 to 2025). The most malignant astrocytic tumor (WHO grade IV). "High NSUN6 expression yields survival benefits in glioblastoma and other cancers." (PMID 41462962, 2025). "NSUN6 m5C is lost in PDX with temozolomide-resistant glioblastoma." (PMID 41462962, 2025). "NSUN6 controls glioblastoma response to temozolomide (TMZ) through NELFB and RPS6KB2 interaction." (PMID 37934565, 2023). "For example, NSUN6 affected the response to temozolomide therapy through the m5C-mediated regulation of NELFB and RPS6BK2 mRNA expression in glioblastoma." (PMID 39340806, 2024). "We also studied the expression of RNA:m5C methyltransferases in glioblastomas (GBM) stratified by IDH mutant status, and findings indicated that NSUN5, NSUN6, and NSUN7 were still differentially expressed." (PMID 32974125, 2020).
lung carcinoma (4 papers, 2024 to 2025). "In lung cancer cells, NSUN6 regulates NM23-H1 expression through m5C modification of the NM23-H1 mRNA 3′UTR." (PMID 41462962, 2025). "NSUN6 positively regulated NM23-H1 expression through m5C modification and inhibited lung cancer cell proliferation, migration, and EMT." (PMID 41462962, 2025). "However, the levels of NSUN6 are low in lung cancer, and NSUN6 may play a protective role." (PMID 40860147, 2025). "NSUN6 expression is reduced in A549, PC9, H1299, and H1975 lung cancer cells." (PMID 41462962, 2025).
triple-negative breast carcinoma (4 papers, 2022 to 2025). An invasive breast carcinoma which is negative for expression of estrogen receptor (ER), progesterone receptor (PR), and human epidermal growth factor receptor 2 (HER2). "In triple-negative breast cancer (TNBC), changes in the expression of m5C RNA methylation regulators, with upregulation of NSUN2 and downregulation of NSUN6, can significantly predict clinical prognosis risk in TNBC patients." (PMID 40370440, 2025). "NSUN2 and NSUN6 have been identified as risk and protective factors, respectively, in triple-negative breast cancer (TNBC) and have been associated with six major immune cells, with the highest correlation between NSUN6 and CD4+ T cells." (PMID 37485079, 2023). "As these are m5C methyltransferases of mRNA, correlations between NSUN2 and NSUN6 have been analyzed using bioinformatics, which have shown them to be positively correlated, uncorrelated and negatively correlated in renal cancer, triple-negative breast cancer, and cutaneous melanoma, respectively." (PMID 35562754, 2022). "In triple-negative breast cancer (TNBC), upregulated NSUN2 acts as an oncogenic factor, while downregulated NSUN6 functions as a tumor suppressor." (PMID 40370440, 2025). "In triple-negative breast cancer (TNBC), NSUN2 expression is upregulated thereby acting as a tumor-promoting factor, whereas NSUN6 is downregulated as a tumor suppressor." (PMID 35562754, 2022).